YY1 (YY1 transcription factor)
Diseases named in the same sentence as YY1 in open-access papers (continued):
Sharing a sentence is not in itself a finding about the gene and the disease.
gastric cancer (continued). "Herein, we investigated the role of transcription factor Yin Yang 1 (YY1), a multi-functional protein, in tumorigenesis of gastric cancer cells." (PMID 24970812, 2014). "Overexpression of miR-34 family suppressed carcinogenesis through down-regulation of YY1 in NUGC-3 gastric cancer cells scarcely expressing miR-34 family." (PMID 24970812, 2014). "Knocking down YY1 in gastric cancer cells suppressed proliferation by inhibiting Wnt/β-catenin pathway, whereas its overexpression exerted oncogenic property by activating Wnt/β-catenin pathway." (PMID 24674326, 2014). "The xenografted tumor growth in the case of subcutaneous injection with SC-M1 cells in nude mice was also checked to assess the function of miR-34 family-YY1 axis in tumor growth of gastric cancer cells in vivo." (PMID 24970812, 2014). "To further investigate the YY1 functions in gastric cancer cells, we overexpressed YY1 into AGS, MKN28 and NCI-N87 cells." (PMID 24674326, 2014). "YY1 is aberrantly expressed in several cancers and also up-regulated in gastric cancer as well as SIIA gastric cancer cells." (PMID 24970812, 2014). "The effect of YY1 and miR-34 family on the ultra-structure of tumorspheres in gastric cancer cells was also examined by scanning electron microscope." (PMID 24970812, 2014). "All members of miR-34 family target 3'-UTR of YY1 mRNA and down-regulate the expression of YY1 in gastric cancer cells." (PMID 24970812, 2014). "This was indicated by YY1 overexpression enhanced cell proliferation, monolayer colony formation and xenograft growth whereas YY1 knockdown inhibited gastric cancer cell proliferation both in vitro and in vivo." (PMID 24674326, 2014). "We demonstrate herein that miR-34 family-YY1 axis is involved in the development and progression of gastric cancer cells in vitro and in vivo." (PMID 24970812, 2014). "To determine the clinical relevance of YY1 in primary GACs, we examined the protein expression of YY1 in 247 clinical gastric cancer samples." (PMID 24674326, 2014). "YY1 is highly expressed in gastric cancer (GC), raising interest in its role in GC." (PMID 40088083, 2025). "However, the function of YY1 and the potential mechanisms through which it operates in gastric cancer (GC) progression by regulating autophagy remains poorly understood." (PMID 37724907, 2023). "YY1 plays a vital biological role in the remodeling and regulation of angiogenesis, tumor metabolism, and immunity in the microenvironment of a great variety of tumors, including gastric cancer." (PMID 37762277, 2023). "ING5 had positive relationships with SRF and YY1 expression in gastric cancer (P<0.05)." (PMID 35747809, 2022). "To address the hypothesis that YY1 might influence the MMP-14 expression, we performed the YY1 over-expression and knockdown experiments in gastric cancer cells." (PMID 28827574, 2017). "The fact that ectopic expression of miR-584-3p was sufficient to prevent the gastric cancer cells from YY1-mediated biological behaviors indicates that the tumor suppressive functions of miR-584-3p are exerted, at least in part, through inhibiting the YY1 activity in gastric cancer." (PMID 28827574, 2017). "Moreover, treatment with GSK343 and A-366 prevented the gastric cancer cells from increased enrichment of H3K27me3 and H3K9me2 and decreased binding of YY1 to MMP-14 promoter induced by miR-584-3p over-expression." (PMID 28827574, 2017). "Taken together, these results indicated that YY1 may play an important regulatory role in the transcription of ATP6V1A in gastric cancer cells." (PMID 28592880, 2017). "In this study, our data showed that YY1 facilitated the in vitro and in vivo growth, metastasis, and angiogenesis of gastric cancer cells, and patients with high expression of YY1 had lower survival probability, indicating the oncogenic functions of YY1 in gastric cancer progression." (PMID 28827574, 2017).
gastric cancer (continued). "Notably, mining of publicly available Gene Expression Omnibus (GEO) datasets indicated that YY1 expression was positively correlated with MMP-14 levels in different gastric cancer cohorts 17–19." (PMID 28827574, 2017). "Subsequently, it was further addressed whether YY1 is involved in the maintenance of cancer stem-like phenotype in gastric cancer cells by examining the ability of tumorsphere formation." (PMID 24970812, 2014). "The current study also suggested that YY1 affected Wnt signaling cascades in gastric cancer cells." (PMID 24674326, 2014). "We further examined whether miR-34 family is involved in controlling tumor development and progression of gastric cancer cells via down-regulation of YY1 herein." (PMID 24970812, 2014). "Up-regulation of YY1 protein was detected in 9 gastric cancer cell lines by Western blot analysis." (PMID 24674326, 2014). "To evaluate the role of YY1 in gastric tumorigenesis, we first sought to check whether YY1 modulates the growth of gastric cancer cells." (PMID 24970812, 2014). "Our data demonstrated that YY1 contributes to gastric carcinogenesis in gastric cancer." (PMID 24674326, 2014). "In gastric cancer, we provide the first evidence that YY1 also plays an oncogenic role." (PMID 24674326, 2014). "YY1 expression was up-regulated in gastric cancer cell lines and primary gastric cancers." (PMID 24674326, 2014). "Besides, LINC00858 facilitated gastric cancer cell metastasis, which could be regulated by transcription factor YY1." (PMID 38410123, 2024). "Our results suggest that the interaction between YY1 with CREB in AGS cells stimulated with H. pylori LPS is involved in the transcriptional initiation and activation of CLDN6, a perfectly defined tight junction protein associated with enhanced gastric cancer progression and invasiveness." (PMID 37762277, 2023). "In addition, YY1 expression was increased in gastric cancer tissues, in line with our results." (PMID 35747809, 2022). "By contrast, miR-584-3p inhibits gastric cancer (GC) progression by suppressing Yin Yang 1 (YY1), which binds to MMP14 promoter to improve its expression." (PMID 35348905, 2022). "The expression and functional role of YY1 in gastric cancer is still unknown." (PMID 24674326, 2014). "TRPM2-AS interacts with the transcription factor ELK1 in gastric cancer, while LINC01224 interacts with YY1 in colorectal cancer, both of which influence cell cycle progression and stress responses." (PMID 40149330, 2025). "Future research should aim to address these limitations, thereby providing a more comprehensive understanding of YY1’s role and the therapeutic potential of IFN-a in gastric cancer." (PMID 38347631, 2024). "The results showed that the expression level of YY1 was significantly increased in 14 tumors, including ESCA, gastric cancer, and liver cancer." (PMID 35359580, 2022). "YY1 directly binds to CCDC43 and ADRM1 gene promoters, leading to their overexpression, and subsequently the aggressiveness of gastric cancer." (PMID 35747809, 2022). "Like YY1, FOXP2 appears to play a dual function as an oncogene in several lymphomas, including multiple myeloma, and as a tumor suppressor in gastric cancer." (PMID 35409160, 2022). "Several have already been linked to cancer; for example SP1 is a prognostic factor for lower survival in gastric cancer, PRDM1 to be a tumor suppressor in lymphomas and YY1 as an initiator of tumorigenesis in several malignancies." (PMID 31337866, 2019). "Our data for intronic rs2289590 in AURKB suggest that additional binding of the YY1 sequence-specific DNA-binding factor, when C allele is present within TF binding site, could modify AURKB expression level, which might result in higher susceptibility to gastric cancer occurrence." (PMID 31521144, 2019).
gastric cancer (continued). "In the current study, our findings showed that miR-584-3p recognized its binding site to repress the enrichment of YY1 on MMP-14 promoter, resulting in decreased expression of MMP-14 in gastric cancer cells." (PMID 28827574, 2017). "In summary, we have shown that YY1 is highly expressed and directly binds to the MMP-14 promoter to facilitate its transcription in gastric cancer." (PMID 28827574, 2017). "Nuclear run-on assay demonstrated that stable over-expression or knockdown of YY1 increased and decreased the nascent transcript levels of MMP-14 in gastric cancer cells, respectively." (PMID 28827574, 2017). "We found that genetic ablation of the p65 subunit of NF-κB attenuated the expression of YY1 and downstream target MMP-14, shedding light on a potential approach to regulate the MMP-14 expression in gastric cancer." (PMID 28827574, 2017). "The expression levels of YY1 and MMP-14 were higher in gastric cancer cell lines, when compared to those in normal gastric epithelial cells." (PMID 28827574, 2017). "A positive correlation between YY1 and MMP-14 transcript levels was noted in gastric cancer tissues (correlation coefficient R = 0.625, P < 0.001)." (PMID 28827574, 2017). "RNAi-mediated knockdown and over-expression of YY1 in HGC-27 and AGS gastric cancer cells in a reporter gene system led to corresponding changes in ATP6V1A mRNA and protein expression." (PMID 28592880, 2017). "Alternatively, knockdown of miR-34 family promoted tumorigenesis via up-regulation of YY1 in SC-M1 and AZ521 gastric cancer cells with higher levels of miR-34 family." (PMID 24970812, 2014). "In the current study, we aimed to investigate the functional role of YY1 in GAC and to examine its clinical significance in gastric cancer patients." (PMID 24674326, 2014). "Our study offers valuable insights into the role of YY1 in the progression and prognosis of gastric cancer, yet it is not without its limitations." (PMID 38347631, 2024). "In gastric cancer cells, either SRF or YY1 silencing decreased ING5 mRNA and protein expression." (PMID 36425530, 2022). "YY1 then binds to PCIF1 promoter to upregulate PCIF1 and promote gastric cancer progression." (PMID 34857012, 2021). "In gastric cancer, DDX3X binds the transcription factor YY1 (yin yang 1) with the help of the circRNA circ-CTNNB1, which results in the transactivation of YY1 and the subsequent activation of genes involved in WNT/β-catenin signalling, thereby promoting tumour progression." (PMID 33627125, 2021). "In this study, through an integrative approach to mine public datasets, we identified Yin Yang 1 (YY1) and miRNA-584-3p (miR-584-3p) as crucial transcriptional regulators of MMP-14 expression in gastric cancer, with their adjacent targeting sites within the MMP-14 promoter." (PMID 28827574, 2017). "YY1 expressions were decreased after infection with miR-34a- or miR-34bc-expressing adenoviruses by Western blot analysis in SC-M1, AZ521, KATO III, NUGC-3, and AGS gastric cancer cells." (PMID 24970812, 2014). "YY1 mRNA also showed positive expression in 9 gastric cancer cell lines, but there was no obvious expression in 5 normal gastric tissues." (PMID 24674326, 2014). "In total, 101 of 247 samples (40.9%) of gastric cancer cases had negative/weak (0 to 1+) YY1 expression, while 146 of 247 samples (59.1%) had strong YY1 expression (2+ to 3+)." (PMID 24674326, 2014). "MMP-14 plays a crucial role in cell invasion; hence, when YY1-induced MMP-14 expression is suppressed by miR-584-3p through methylation of the YY1 binding site in the MMP-14 promoter, the tumorigenesis and aggressiveness of gastric cancer cells were suppressed." (PMID 37444616, 2023).
gastric cancer (continued). "Furthermore, miR-584-3p is under-expressed in human gastric cancer, and suppresses the transcription of MMP-14 via epigenetically suppressing the binding of YY1 to its promoter, resulting in decreased growth, invasion, metastasis, and angiogenesis of gastric cancer cells in vitro and in vivo." (PMID 28827574, 2017). "In this study, the functional role of YY1 in gastric cancer was investigated by MTT proliferation assays, monolayer colony formation, cell cycle analysis, signaling pathway analysis, Western blot analysis and in vivo study through YY1 knockdown or overexpression." (PMID 24674326, 2014). "YY1 nuclear expression correlated with poor prognosis in patients with early stage GAC, suggesting that YY1 might potentially serve as a prognostic biomarker and a therapeutic target in gastric cancer." (PMID 24674326, 2014). "Studies have shown that miR-134-5p functions by targeting Yin Yang 1 (YY1) signaling, which can alter the growth and apoptosis of gastric cancer (GC) cells, thereby highlighting its potential as a therapeutic target for GC." (PMID 38008726, 2023). "The lack of effect on UBC and UBB gene transcription in HSF1-silenced gastric cancer cells may depend on the fact that HSF1 is a stress-activated TF, while for YY1 we evaluated different target genes in the siYY1-transfected cells and we found that they are differently affected by YY1 knockdown." (PMID 32751694, 2020). "In addition, several reports have demonstrated the pro-survival and pro-carcinogenetic role of YY1, SP1 and HSF1 in gastric cancer (GC) development." (PMID 32751694, 2020). "Importantly, YY1 directly bond to MMP-14 promoter to increase its expression, resulting in elevated levels of VEGF and active MMP-2, but not of Snail, in gastric cancer cells." (PMID 28827574, 2017).
melanoma (43 papers, 2012 to 2025). A malignant, usually aggressive tumor composed of atypical, neoplastic melanocytes. "Melanoma has been shown to have a high susceptibility to YY1 deregulation as heterozygous loss of YY1 significantly reduced tumor burden and increased survival." (PMID 41327312, 2025). "In contrast, YY1—an established regulator of tumor immunomodulation—exhibited consistent predictive power: elevated YY1 expression was associated with shorter OS in melanoma and glioblastoma patients receiving anti‐PD‐1 therapy." (PMID 41322030, 2025). "In relation to this, one study established YY1 is not only essential for primary melanoma formation, but its loss also promotes metastasis." (PMID 41327312, 2025). "Increased expression of EZH2 has been associated with elevated level of Yin Yang 1 (YY1) transcription factor in melanoma TILs." (PMID 37325482, 2023). "YY1 promotes tumor growth in melanoma as a conditional ablation of one YY1 allele; in a melanoma mouse model, it prevents tumorigenesis." (PMID 37568827, 2023). "Zhou and colleagues showed that the overexpression of YY1 increases cell survival in melanoma cells, and the knockout of YY1 was associated with decreases in cell proliferation and migration." (PMID 37686541, 2023). "It was shown that the level of MX2 expression is critically mediated by YY1 further underlying the role of YY1 in melanoma." (PMID 35719931, 2022). "To provide further evidence that YY1 is a transcriptional regulator of translation genes we analyzed two publicly available datasets in murine pro‐B cells and human melanoma cells generated using a conditional YY1 allele and YY1 siRNA, respectively." (PMID 35514210, 2022). "High levels of NGFR were also associated with other metabolic stress inducers, further indicating that YY1 knockdown mimics a metabolic stress program associated with an increased invasion potential in melanoma." (PMID 35693944, 2022). "And in some cancers, the expression of YY1 is affected by mutations in certain genes; for example, in melanoma, the expression of YY1 is reduced by NOX3 and RTCB mutations." (PMID 35791393, 2022). "Extensive research also revealed that YY1 deletion in the tamoxifen-inducible endothelial cell-specific YY1 deficient mouse model inhibited angiogenesis and the melanoma growth." (PMID 35719931, 2022). "Accordingly, while counteracting tumor growth, loss of YY1 strongly promoted melanoma cell invasiveness in vitro and metastasis formation in melanoma mouse models in vivo." (PMID 35693944, 2022). "To support this idea, we exposed human melanoma cells to different metabolic stressors that we have previously found to be associated with loss of YY1." (PMID 35693944, 2022). "A high level of YY1 expression was noted in tumor cells and tumor-associated endothelial cells in human melanoma tissues." (PMID 35719931, 2022). "The results of the experiments in a mouse melanoma model expressing human oncogene N-RasQ61K only in melanocytic lineage on an INK4a-deficient background demonstrated that YY1 is coexpressed with a melanocytic marker in both hair follicles and skin melanomas." (PMID 33728560, 2021). "Ablation of only one YY1 allele was sufficient to inhibit melanoma formation, indicating that melanogenesis is linked to YY1 expression." (PMID 33728560, 2021). "A significant level of YY1 expression was observed in both in tumor cells and tumor-associated ECs in human melanoma tissues." (PMID 33235311, 2020). "In a more recent report, the role of YY1 in melanoma tumorigenesis has been directly shown using melanoma mouse model, in which ablation of one YY1 allele impaired melanoma tumor growth by regulating metabolism and protein translation." (PMID 31824839, 2019). "The overexpression of YY1 might be associated with melanoma progression, as it is involved in many biological processes, including modulation of the immune response, apoptosis, epithelial to mesenchymal transition, angiogenesis, and metastasis formation." (PMID 35719931, 2022).